CYLD (CYLD lysine 63 deubiquitinase)
Diseases named in the same sentence as CYLD in open-access papers (continued):
Sharing a sentence is not in itself a finding about the gene and the disease.
melanoma (39 papers, 2011 to 2025). A malignant, usually aggressive tumor composed of atypical, neoplastic melanocytes. "NRIR, firstly found to be associated with melanoma by our study, was positively correlated with CYLD, MLKL, STAT1, and TNFSF10." (PMID 37147395, 2023). "Loss of CYLD was shown to enhance the metastatic propensities of Grm1 driven melanoma cells by increasing their migratory, angiogenic and vascular mimicry potential." (PMID 34359771, 2021). "Subsequent studies have linked the loss of CYLD to the pathogenesis of several other tumors, including melanoma, breast cancer, T-lymphoblastic leukemia, and colon and hepatocellular carcinoma." (PMID 32024820, 2020). "Loss of CYLD activity has been correlated with more aggressive behavior in cutaneous squamous cell carcinoma, melanoma, pancreatic carcinoma, and hepatocellular carcinoma." (PMID 32461623, 2020). "Experiments using cell lines generated from both primary and metastatic melanoma tissue of Tg(Grm1) Cyld−/− and Tg(Grm1) Cyld+/+ mice confirmed that loss of CYLD enhances the proliferative and migratory potential, as well as the clonogenicity in vitro." (PMID 31591386, 2019). "In this study, a mouse model was newly developed to investigate the impact of CYLD deficiency on melanoma." (PMID 31591386, 2019). "Bosserhoff and colleagues showed that a homozygous loss of CYLD led to a shortened latency in melanoma development and progression in our Grm1-driven spontaneous melanoma mouse model Tg(Grm1)EPv, as well as increased vasculogenic mimicry and lymph angiogenesis." (PMID 36139432, 2022). "Moreover, significant amounts of clinical study have demonstrated the loss of CYLD expression in a variety of malignant tumors, such as, hepatocellular carcinoma, melanoma, basal cell carcinoma, breast cancer, glioblastoma, and cholesteatoma." (PMID 36376983, 2022). "A recent report proposed that the loss of CYLD in melanoma cells leads to the upregulation of euchromatic histone-lysine N-methyltransferase 2 (EHMT2), which is associated with the di-methylation of H3K9 and heterochromatin formation and contributes to increased tumor proliferation." (PMID 36139432, 2022). "At the molecular level, some mechanisms are maintained, such as activation of NF-κB and JNK/AP-1/β1-integrin pathways in response to CYLD gain and loss of function that could explain the observed melanoma tumorigenesis." (PMID 35884430, 2022). "Thus, depleting CYLD in melanoma cells leads to an increase in RIPK1 associated with an increase in K63-related polyubiquitination of RIPK1." (PMID 35884430, 2022). "Based on our results, loss of CYLD positively affects the formation of lymph vessels in melanoma and enhances metastasis, supporting the important role of CYLD especially in the early process of melanoma progression." (PMID 31591386, 2019). "However, CYLD has been implicated in the control of melanoma tumorigenesis in vivo." (PMID 35884430, 2022). "To validate that loss of CYLD activity results in enhanced resistance to T cells we generated CYLD knockout melanoma lines and tested them in our matched co-culture assay." (PMID 41315176, 2025). "Earlier studies from our lab showed constitutive activation of NF-κB in mGluR1-positive melanoma cells, further suggesting a link between mGluR1 and CYLD/NF-κB." (PMID 38672652, 2024). "Various studies have reported that CYLD suppressed cancer progression in different types of tumors, such as melanoma and non-small cell lung cancer." (PMID 38246916, 2024). "In melanoma, non-small cell lung cancer and breast cancer, CYLD was shown to inhibit tumor cell migration and invasion." (PMID 38246916, 2024). "Similar research has shown that miR-767 promoted cell proliferation in human melanoma by suppressing CYLD expression." (PMID 36409439, 2023). "Another mechanism that reduces CYLD expression is BRAF-mediated ERK (MAPK) activation via the transcription factor SNAIL1 (SNAI1) in melanoma." (PMID 37387450, 2023).
melanoma (continued). "CYLD expression is downregulated through a range of mechanisms in melanoma, breast cancer, haematologic malignancies, colon cancer, hepatocellular cancer, neuroblastoma and basal cell prostate cancer." (PMID 37387450, 2023). "We have shown that NF-κB is constitutively active in our mGluR1-expressing melanoma cells, suggesting the potential involvement of mGluR1 in the CYLD–NF-κB axis." (PMID 36139432, 2022). "Recently, CYLD has been shown to participate in the tumorigenicity of melanoma cells through its important role in regulating the MAPK pathway by modifying lysine-63 (K63)-linked polyubiquitinated chains for ERK1/2." (PMID 35884430, 2022). "Recently, deubiquitinase cylindromatosis (CYLD), a well-known tumor suppressor, was demonstrated to be another player in melanoma progression and invasion." (PMID 36139432, 2022). "CYLD expression was shown to be inversely correlated with overall and progression-free survival in melanoma patients." (PMID 35884430, 2022). "The Bosserhoff group used our Grm1-driven mouse model, TG(Grm1)Epv, to elucidate the function of the tumor suppressor gene, deubiquitinase cylindromatosis (CYLD), in melanoma development and progression." (PMID 34359771, 2021). "CYLD −/− TG(Grm1)Epv mice showed early melanoma onset and tumor progression compared to CYLD +/+ TG(Grm1)Epv mice." (PMID 34359771, 2021). "Recently, the role of CYLD was investigated in a murine model (Grm1) for spontaneous melanoma development." (PMID 33800394, 2021). "In the present study, MiR-767 has been found to promote cell proliferation in human melanoma by suppressing CYLD expression." (PMID 34900997, 2021). "Coexpression of a constitutively active MKK7 or c-Jun mutant overcame CYLD-inhibition of melanoma growth and metastasis." (PMID 32252279, 2020). "miR‐767 is up‐regulated in human melanoma tissues and cell lines, which promote melanoma cell proliferation, and miR‐767 acts as a tumor promoter in human melanoma by targeting CYLD." (PMID 32961635, 2020). "In melanoma, the MALT1, MKK4/7, and JNK/AP1 signaling cascade promotes melanoma cell proliferation and migration, whereas CYLD inhibits it." (PMID 32252279, 2020). "Restoration of CYLD expression in metastatic human melanoma cell lines inhibited melanoma xenograft growth in the skin and lung following subcutaneous and tail-vein injections, respectively." (PMID 32252279, 2020). "In accordance with these findings, JNK activation is increased in the majority of malignant melanoma cell lines, and tissues examined, which was correlated with decreased expression of CYLD." (PMID 32252279, 2020). "As vasculogenic mimicry is a well-known feature of melanoma, the impact of CYLD on melanoma cells to form vascular tubes was analyzed." (PMID 31591386, 2019). "In this study, we analyzed the role of CYLD for the first time in a murine model for spontaneous melanoma development." (PMID 31591386, 2019). "The deubiquitinase cylindromatosis (CYLD) is a well-known tumor suppressor, found to be down regulated in many cancer types including breast cancer, colon carcinoma and malignant melanoma." (PMID 31591386, 2019). "First, we investigated the role of CYLD in the formation of lymphatic vessels via immunofluorescence staining on murine Tg(Grm1) Cyld+/+ and Cyld−/− melanoma tissues using LYVE-1, a specific lymphatic endothelial marker." (PMID 31591386, 2019). "This difference hints to a specific function of CYLD in different cell types and supports a role of CYLD in vascular mimicry of melanoma cells." (PMID 31591386, 2019). "Here, a novel function for CYLD in both vasculogenic mimicry and lymph angiogenesis in melanoma was characterized." (PMID 31591386, 2019). "In melanoma, the repression of CYLD by the transcription factor Snail1 contributes to cell proliferation and cancer invasiveness in vitro and tumor progression and metastasis in vivo." (PMID 31122251, 2019).
melanoma (continued). "In summary, the newly generated mouse model and the resulting cell lines of primary tumors and metastases represent a good base for studies of the function of CYLD in malignant melanoma." (PMID 31591386, 2019). "In this study, we revealed that CYLD has a regulatory role in vasculogenic mimicry of melanoma cells by suppressing tubular formation." (PMID 31591386, 2019). "CYLD is suppressed in human melanoma cells by the transcriptional repressor SNAIL1 leading to an increase of their proliferative, invasive and migratory potential." (PMID 31591386, 2019). "On the basis of the RNA sequencing results and to gain further insight into how CYLD acts as tumor suppressor in malignant melanoma, cell lines of both Tg(Grm1) Cyld-wildtype and Tg(Grm1) Cyld-knockout mice were generated." (PMID 31591386, 2019). "In summary, our findings reveal new functional aspects of CYLD in the process of (lymph-) angiogenesis and demonstrate its importance in the early process of melanoma progression." (PMID 31591386, 2019). "In this research, we confirmed that MEG3 played antitumor role in malignant melanoma development through miR-499-5p/CYLD axis." (PMID 29808164, 2018). "The expression of CYLD was reduced and the level of miR-499-5p was elevated in melanoma tissues and cell lines." (PMID 29808164, 2018). "CYLD has been identified to be downregulated in melanoma tissues and cell lines and to suppress melanoma cell proliferation and metastasis by blocking the JNK/AP-1 and β1-integrin signaling pathways." (PMID 29808164, 2018). "This was reversed by co-overexpression of RIP1, suggesting that downregulation of CYLD is responsible for upregulation of RIP1 in melanoma cells with acquired resistance to BRAF inhibitors." (PMID 29880840, 2018). "The combined results identified that MEG3 suppressed melanoma cell proliferation and invasion by regulating the expression of CYLD mediated by sponging miR-499-5p." (PMID 29808164, 2018). "In this report, the expression and function of MEG3, miR-499-5p, and CYLD were explored in melanoma tissues and cell lines." (PMID 29808164, 2018). "Further analysis validated that the level of miR-499-5p was inversely associated with CYLD level and MEG3 expression in melanoma tissues and cell lines." (PMID 29808164, 2018). "In support, CYLD is reduced in post-treatment fresh melanoma isolates with increased levels of RIP1 compared with paired pre-treatment samples." (PMID 29880840, 2018). "The involvement of JNK in cancer progression can be supported by the fact that suppression of JNK activation by tumor suppressor cylindromatosis (CYLD) inhibits melanoma progression." (PMID 27485778, 2016). "In skin cancers such as basal cell carcinoma and melanoma, CYLD was repressed at the transcriptional level by the activation of Snail." (PMID 24495516, 2014). "The tumor suppressor CYLD is downregulated in many types of cancer, including gliomas, basal cell carcinoma, melanoma, T-cell leukemia, and colon and hepatocellular carcinomas." (PMID 24495516, 2014). "Beside cylindromatosis, the expression of CYLD is dramatically down-regulated in other types of human cancer such as melanoma, cervix cancer, colon cancer and multiple myeloma." (PMID 21573132, 2011). "We have reported earlier that CYLD by retaining Bcl-3 in the cytoplasm reduces the expression of cyclin-D1 and consequently decreases the proliferation of keratinocytes and melanoma cells." (PMID 21573132, 2011). "A connection between CYLD expression and the onset of melanoma was demonstrated with Tg(Grm1)EPv." (PMID 38672652, 2024). "The mechanistic dissection of the role of CYLD in cancers apart from melanoma is likely to continue to expand and may reveal disease-specific pathogenic roles." (PMID 37387450, 2023).
melanoma (continued). "Initial investigations into the role of CYLD in malignant melanoma have shown that its transcript or protein level is strongly decreased in primary or metastatic melanomas compared to normal human epidermal melanocytes in vitro as well as in vivo on immunohistochemistry sections." (PMID 35884430, 2022). "In addition, melanoma-derived point mutants of CYLD (F675S, P698L, and D681G) also lose the ability to remove ubiquitin chains from ERK1." (PMID 35884430, 2022). "CYLD (cylindromatosis-associated DUB) belongs to the USP class of cysteine proteases and is identified as a tumor suppressor on account of its loss of function correlated with several cancers including melanoma." (PMID 35884430, 2022). "CYLD is suppressed in human melanoma cells, by the transcription factor SNAIL1." (PMID 33800394, 2021). "Tg(Grm1)/Cyld−/− mice autochthonously developed melanoma mainly on the tail and ears, due to an increased expression of the metabotropic glutamate receptor 1 (GRM1) under the control of the melanocyte specific Dct (Trp-2) promoter, and a lack of the tumor suppressor cylindromatosis (CYLD)." (PMID 34830742, 2021). "Additionally, how does mGluR1 positive melanoma cells regulate CYLD, and what prompts the temporal inactivation of CYLD by mGluR1 expressing melanoma cells?" (PMID 34359771, 2021). "Additionally, lncRNA MEG3 was also explored in the development of melanoma, e.g., lncRNAMEG3 suppresses the proliferation and invasion of melanoma by regulating CYLD expression mediated by sponging miR-499-5p." (PMID 31938020, 2020). "Furthermore, CYLD expression was shown to be inversely correlated with overall and progression-free survival in melanoma patients." (PMID 31591386, 2019). "As melanoma cells metastasize predominantly via lymphatic vessels into lymph nodes or distant organs, we aimed at understanding the relevant factors modulated by CYLD in this process." (PMID 31591386, 2019). "Finally, our new findings constitute a step forward in understanding the specific role of the tumor suppressor CYLD in malignant melanoma." (PMID 31591386, 2019). "In addition, we present data that indicate a new regulatory role of CYLD regarding vasculogenic mimicry and (lymph-) angiogenesis in malignant melanoma." (PMID 31591386, 2019). "CYLD is known to have a tumor-suppressive role in human melanoma." (PMID 31591386, 2019). "Our data indicate that loss of CYLD contributes to angiogenesis in melanoma by a potential negative effect on expression of several anti-angiogenic factors like TIMP-2, TIMP-3 and ADAMTS5." (PMID 31591386, 2019). "Furthermore, our findings demonstrate the crucial impact of CYLD on melanoma onset, progression and metastasis, as well as its multiple tumor-suppressive functions." (PMID 31591386, 2019). "In search for the mechanism(s) responsible for downregulation of CYLD in melanoma cells with acquired resistance to BRAF inhibitors, we found that Snail1, which is known to transcriptionally repress the expression of CYLD22, was increased in resistant melanoma cells." (PMID 29880840, 2018). "For example, inhibition of CYLD expression enhanced human malignant melanoma growth and invasion." (PMID 29808164, 2018). "Importantly, ERK activation also appeared to play a role in maintaining RIP1 expression through upregulation of Snail1 and downregulation of CYLD in melanoma cells acquired resistance to BRAF/MEK inhibitors." (PMID 29880840, 2018). "Interestingly, in melanoma cells, SNAIL has been shown to inhibit expression of CYLD, which in turn leads to increased melanoma proliferation and invasion." (PMID 27448979, 2016). "In addition, TRAIP interacts with CYLD and Syk, two tumor suppressors implicated in the formation of skin appendages tumors such as cylindroma, trichoepithelioma and spiradenoma (CYLD) and of melanomas and breast tumors (CYLD and Syk)." (PMID 26369285, 2015).
melanoma (continued). "Because CYLD has a central role in inflammation, cell death, cell cycle progression, cell migration, DNA damage, and WNT signaling, CYLD loss-of-function is associated with the deregulation of NFκ-B, JNK, c-MYC, and AKT and consequent tumor development, such as melanoma, leukemias, and TETs." (PMID 33915954, 2021). "Functionally, upregulation of MEG3 inhibited melanoma cell proliferation, invasion, and migration, enhanced melanoma cell apoptosis, arrested melanoma cell cycle, and regulated the expression of E-cadherin, N-cadherin, and cyclin D1 by regulating CYLD expression mediated by sponging miR-499-5p." (PMID 29808164, 2018). "BOK and CYLD were down-regulated, and CD14 and FASLG were up-regulated in melanoma samples, which were in accordance with the bioinformatics results." (PMID 35387121, 2022). "Strikingly, Snail1-mediated suppression of CYLD played a crucial role in promoting RIP1 expression upon ERK activation, particularly, in melanoma cells with acquired resistance to BRAF inhibitors." (PMID 29880840, 2018). "Our results suggest that the tumor suppressive role of CYLD is, at least in part, due to its inhibitory effect on the expression of RIP1 and subsequent reduction in activation of NF-κB in melanoma cells." (PMID 29880840, 2018). "Several investigations have reported that the potential to trigger necroptosis in melanoma might be inhibited due to low expression levels of both CYLD and RIPK3 in melanoma cell lines." (PMID 38336727, 2024). "Conversely, CYLD expression has been suggested to be downregulated because of elevated SNAIL1 expression, resulting in increased levels of CCND1(Cyclin-D1) and CDH2 (N-Cadherin) and enhanced proliferation, migration, and invasion of human melanomas." (PMID 35884430, 2022). "This inverse correlation between CYLD and ERK1/2 activation is observable by immunohistochemistry on human melanoma samples with a preference for a decreased CYLD transcript in highly metastatic melanoma and is associated with poor survival in melanoma patients." (PMID 35884430, 2022). "Several studies have indicated that inducing necroptosis in melanoma may be limited as it was found that both CYLD and RIPK3 were poorly expressed in melanoma cell lines, although melanocytes and benign nevi expressed RIPK3 at a high level." (PMID 32340261, 2020). "Interestingly, melanoma tissue of Cyld-knockout mice exhibits more LYVE-1 positive vessels than the control group, thus CYLD is involved in the process of lymph angiogenesis." (PMID 31591386, 2019). "Moreover, we demonstrate that suppression of CYLD by ERK1/2 signaling plays an important role in maintaining RIP1 expression, and that melanoma cells with acquired resistance to BRAF inhibitors are more critically dependent on RIP1 for survival." (PMID 29880840, 2018). "Taken together, CYLD mediated, at least in part, the effect of MEG3 on tumorigenesis of melanoma." (PMID 29808164, 2018). "It was identified that the level of MEG3 and CYLD was significantly decreased, but the expression of miR-499-5p was dramatically increased in melanoma tissues and cell lines compared with paired nontumor tissues or HEMa-LP cells." (PMID 29808164, 2018). "Since the expression of CYLD is transcriptionally repressed by Snail122, and downregulation of CYLD results in an increase in RIP1 in melanoma cells, we examined whether ERK1/2-mediated expression of RIP1 is related to suppression of CYLD by Snail1." (PMID 29880840, 2018). "Indeed, we found that downregulation of CYLD, which is one of the deubiquitinases of RIP1, was responsible for upregulation of RIP1 in melanoma cells with acquired resistance to BRAF inhibitors." (PMID 29880840, 2018). "Furthermore, CYLD expression is not influenced by either origin or genetic background and remains highly heterogeneous both in melanoma cells and in fresh tissue melanoma progression." (PMID 35884430, 2022).